ZFTA (zinc finger translocation associated)
Synonyms: C11orf95; MGC3032
Tractability: PROTAC: UniProt records ubiquitination sites on it.
Gene: Protein-coding gene on chromosome 11 (63,759,892 to 63,768,795, reverse strand). Ensembl gene ENSG00000188070.
Subcellular location (Human Protein Atlas): Intermediate filaments
Gene Ontology:
Biological process: negative regulation of DNA-templated transcription
Cellular component: nucleus
Genetic constraint (gnomAD): Loss-of-function variants: 33 observed, 27.51 expected, observed/expected ratio (o/e) 1.2, 90% interval 0.91 to 1.6. The synonymous counts are far from expectation, so gnomAD's model fits this gene poorly and the ratio says little. Missense variants: 943 observed, 772.29 expected, observed/expected ratio (o/e) 1.22, 90% interval 1.16 to 1.29. Synonymous variants: 508 observed, 346.64 expected, observed/expected ratio (o/e) 1.47, 90% interval 1.36 to 1.58.
Homologues: Orthologues: chimpanzee ZFTA (99% identical), macaque ZFTA (98% identical), pig ZFTA (91% identical), mouse Zfta (89% identical), rat Zfta (89% identical), dog ZFTA (87% identical), guinea pig ZFTA (85% identical), tropical clawed frog zfta (38% identical), zebrafish zfta (28% identical).
Diseases named in the same sentence as ZFTA in open-access papers:
ZFTA is named in the same sentence as 21 diseases in open-access papers, as found by Europe PMC text mining. Sharing a sentence is not in itself a finding about the gene and the disease. The quoted sentences say what the papers report.
ependymoma (37 papers, 2015 to 2025). A WHO grade II, slow growing tumor of children and young adults, usually located intraventricularly. "Over 95% of ependymomas that arise in the cortex are driven by a gene fusion involving the zinc finger translocation-associated (ZFTA) protein." (PMID 40866513, 2025). "The ependymomas are classified on the basis of specific gene alterations, such as ZFTA or YAP1 fusions being characteristic in supratentorial ependymomas, and MYCN amplification being the norm in spinal ependymomas." (PMID 40677455, 2025). "We further observed that, except for three outliers, C11orf95::RELA (ZFTA::RELA) fusion-positive ependymomas fell within distinct clusters." (PMID 37492101, 2023). "Supratentorial ependymomas are divided into ST ependymomas with ZFTA (former RELA-/C11orf95–fusion positive ependymomas), tumors with a YAP1-MAMLD1 fusion, or other rare fusions." (PMID 35455542, 2022). "According to the 2021 WHO classification of CNS tumors, there are two main subsets of supratentorial ependymoma, namely the ZFTA (also called C11orf95) and the YAP1 fusion positive supratentorial ependymomas." (PMID 37213274, 2023). "Within the supratentorial compartment, two molecularly defined types of ependymoma are characterized by recurrent gene fusions, one involving the gene ZFTA (formerly referred to as C11orf95, most frequently fused to RELA), and the other involving YAP1." (PMID 34355256, 2021). "In addition, supratentorial ependymomas most commonly harbored the C11orf95 – RELA fusion (71% of tumors, also known as ZFTA-RELA) and meningiomas most frequently harbored fusions in NF2 and YAP1 (both 15% of tumors)." (PMID 36711972, 2023). "This modification reinforces the idea that supratentorial-ependymomas exhibiting fusion that implicates the C11orf95 (now called ZFTA) gene with or without the RELA gene, represent the same histomolecular entity." (PMID 34389065, 2021). "In the present case, the diagnoses of ependymoma and MN1‐altered astroblastoma were excluded because of the lack of perivascular pseudorosettes and ZFTA, YAP1, and MN1 fusions." (PMID 39492623, 2025).
supratentorial ependymoma (4 papers, 2018 to 2023). A high grade ependymoma that is located within the supratentorial brain. "ZFTA-RELA (formerly known as c11orf-RELA) fused supratentorial ependymoma (ZFTAfus ST-EPN) has been recognized as a novel entity in the 2016 WHO classification of CNS tumors and further defined in the recent 2021 edition." (PMID 37287693, 2023).
pediatric cancer (1 paper, 2021). "Our approach has also identified other fusions commonly associated with pediatric cancer, including EWSR1-FLI1 (n = 9), FGFR1-TACC1 (n = 3), PAX3-FOXO1 (n = 3), ZFTA-RELA (n = 2), COL3A1-PLAG1 (n = 2), and NPM1-ALK (n = 2)." (PMID 34863095, 2021).
ZFTA also shares sentences with these, for which no sentence is quoted: tumor (9 papers); brain tumor (7); glioma (4); cancer (3); pilocytic astrocytoma (3); anaplastic ependymoma (2); CNS tumors (2); meningioma (2); acute lymphoblastic leukemia (1); astroblastoma (1); brain disease (1); brain ependymoma (1); embryonal tumors (1); ganglioglioma (1); pleomorphic xanthoastrocytoma (1); rhabdoid tumor (1); sarcoma (1); subependymoma (1).